ZNF41 (zinc finger protein 41)
Description:
May be involved in transcriptional regulation.
Synonyms: MGC8941; MRX89
Tractability: PROTAC: UniProt records ubiquitination sites on it; ubiquitination databases record sites on it.
Gene: Protein-coding gene on chromosome X (47,444,693 to 47,483,247, reverse strand). Ensembl gene ENSG00000147124.
Subcellular location: Nucleus
Subcellular location (Human Protein Atlas): Nucleoplasm
Pathways (Reactome):
Gene expression (Transcription): Generic Transcription Pathway
Gene Ontology:
Molecular function: protein binding
Biological process: regulation of DNA-templated transcription
Cellular component: nucleus
Gene-disease validity (ClinGen):
ClinGen rates the evidence that ZNF41 causes each of these diseases.
non-syndromic X-linked intellectual disability (X-linked): Disputed. Nonspecific X-linked intellectual deficiencies (MRX) belong to the family of sex-linked intellectual deficiencies (XLMR).
Homologues: Orthologues: chimpanzee ZNF41 (99% identical), macaque ZNF41 (94% identical), pig ZNF41 (85% identical), dog ZNF41 (83% identical), rabbit ZNF41 (83% identical). Paralogues in human: ZNF484 (51% identical), ZNF585B (49% identical), ZNF175 (47% identical), ZNF585A (46% identical), ZNF658 (42% identical), ZNF33B (42% identical), ZNF605 (41% identical), ZNF182 (41% identical), ZNF630 (40% identical), ZNF197 (39% identical), ZFP28 (38% identical), ZNF300 (38% identical), and 164 more.
Diseases named in the same sentence as ZNF41 in open-access papers:
ZNF41 is named in the same sentence as 2 diseases in open-access papers, as found by Europe PMC text mining. Sharing a sentence is not in itself a finding about the gene and the disease. The quoted sentences say what the papers report.
hepatocellular carcinoma (2 papers, 2024 to 2025). A malignant tumor that arises from hepatocytes. "Zinc finger protein 41 (ZFP41) can suppress the progression and metastasis of hepatocellular carcinoma, and YTHDF3-catalyzed m6A modification of ZFP41 suppresses hepatocellular carcinoma malignant progression by attenuating Snail transcriptional activation." (PMID 40986143, 2025).
ZNF41 also shares sentences with these, for which no sentence is quoted: FG syndrome (1 paper).